CD44 (CD44 molecule (IN blood group))
Diseases named in the same sentence as CD44 in open-access papers (continued):
Sharing a sentence is not in itself a finding about the gene and the disease.
breast carcinoma (continued). "In contrast, in basal cell lines with high percentages of CD44+/CD24- cells (MDA.MB.231, SUM159, and SUM1315), sorting for ESA+ cells is sufficient to enrich for breast cancer-initiating cells." (PMID 18366788, 2008). "We analyzed the presence of CD44 and CD24 antigens on human breast cancer tissues using double-staining immunohistochemistry." (PMID 18559090, 2008). "In the present study, we have explored the dual expression of CD44 and CD24 in a sample of 240 stage II breast tumors with specific regard to breast cancer subtypes." (PMID 18559090, 2008). "All cell lines derived from A1 tumor (A1.1, A1.8, and A1.10) exhibited a higher (1.32% to 5%) fraction of CD44+/CD24- cells, which correlate with the phenotype of human breast cancer stem cells." (PMID 18241344, 2008). "All cell lines derived from one tumor included increased numbers of CD44+/CD24- cells, which were previously identified as human breast cancer stem cells." (PMID 18241344, 2008). "We investigated the importance of the stem/progenitor phenotype defined by CD44 positivity and CD24 negativity for breast cancer cells to invade and metastasize." (PMID 17062128, 2006). "CD44 and CD24 have been shown to regulate invasion and metastasis of breast cancer cells either positively or negatively." (PMID 17062128, 2006). "Five among 13 breast cancer cell lines examined (MDA-MB-231, MDA-MB-436, Hs578T, SUM1315, and HBL-100) contained a higher percentage (>30%) of CD44+/CD24- cells." (PMID 17062128, 2006). "Using POU1F1-overexpressing and knock-down breast cancer cell lines, as well as immunodeficient mouse models, our data demonstrate that POU1F1 induces a BCSC-like phenotype in breast tumor cells by deregulating markers such as CD24, CD44, CD133, and ALDH." (PMID 41857068, 2026). "Regarding CD44, its expression was lower in breast cancer TT compared to NAT, with no significant changes in colorectal cancer." (PMID 41373491, 2025). "Moreover, in recipient breast cancer cells, a significant reduction in cell growth, EMT status, and the cancer stem cell‐enriched CD44+CD24‐ population as observed post‐delivery." (PMID 40059964, 2025). "This flavonol was shown to inhibit the growth of breast cancer stem cells, MCF-7, which are resistant to doxorubicine, through the down-regulation of P-gp expression, Y-box binding protein 1 (YB-1) nuclear protein, and the CD44+/CD24− phenotype." (PMID 39859345, 2025). "Combined high expression of CD44 with low or absent expression of CD24 (CD44hi/CD24lo) is one of the most commonly used markers to identify CSCs in breast cancer." (PMID 40943144, 2025). "Consequently, breast cancer stem cells were evaluated using flow cytometry, revealing that the proportion of CD24-/CD44+ cells was significantly higher in alpelisib-resistant cells compared to parental cells, as well as protein levels of CD44 and c-Myc." (PMID 40303291, 2025). "Furthermore, ligand‐receptor analysis showed that COL1A1/COL1A2‐SDC4/CD44 and MDK/NCL presented the highest communication probability, suggesting that these ligand‐receptor pairs are necessary for LN metastasis in breast cancer." (PMID 40492378, 2025). "This heterogeneity was more clearly visualized through medial sections of these spheroids; in unconfined spheroids, breast cancer cells demonstrated low, diffuse CD44 expression and predominantly lacked CD133 expression." (PMID 40569213, 2025). "Furthermore, ASCs can spontaneously fuse with breast cancer cells, resulting in a population enriched with breast cancer stem cell (CSC) markers such as CD44+CD24−/lowEpCAM+." (PMID 39123496, 2024). "FEZF1-AS1 knockdown decreased the CD44+/CD24- ratio, BCSC cells' capacity to form mammospheres, and the expression of stemness factors (Nanog, OCT4, SOX2), indicating that FEZF1-AS1 silencing has a suppressive effect on the stemness of breast cancer." (PMID 39170516, 2024).
breast carcinoma (continued). "In addition, in the human breast cancer cell line MDA‐MB468, siRNA‐mediated silencing of CD44 was shown to enhance doxorubicin chemosensitivity." (PMID 38783892, 2024). "Culture of breast cancer cells in M2 TAM conditioned media enhanced their invasiveness and migratory ability, induced their mesenchymal phenotype and enriched the cancer stem cell population (CD44+CD24low/- and ALDH+)." (PMID 39044824, 2024). "Indeed, a subpopulation with CD44+ and CD24−/lower phenotype showed increased metastasis to bone in a mouse model of human breast cancer stem-like cells." (PMID 38392969, 2024). "The migratory potential of the sorted CD24+‐breast cancer cells and CD24−/CD44+‐breast CSC populations in the presence of combinatorial treatment of Doxorubicin low dose (0.01 μM) and compound 1e (5 μM) was observed to be significantly reduced as compared to the positive control group (10% FBS)." (PMID 38522013, 2024). "In the liver, gastric, breast cancer, and acute myeloid leukemia (AML), CD44 is a CSC marker." (PMID 39170516, 2024). "Third, HA ishighly biocompatible and can target CD44 overexpressed on breast cancer,including metastatic breast cancer cells.54−56 In our study,NP-ICG-HA exhibited no significant toxicity to cells, indicating itsgood translational potential." (PMID 38757711, 2024). "While CD44+CD24low/neg breast cancer cells were not rare (11–35% of the cell populations) they had >10× higher xenograft initiating capacity than CD44+CD24+ tumor cells." (PMID 37832945, 2024). "CSCs are majorly characterized by the expression of CD44, CD24, ALDH1 and CD133 in breast cancer." (PMID 39062100, 2024). "Additionally, in MCF−7 cells, it has been reported that the inhibition of MTH1 increases the proportion of CD44+ CD24−/Low cell subpopulations, suggesting that MTH1 inhibition enhances the number of breast cancer stem cells." (PMID 38543077, 2024). "This study examines the effects of oxygen conditions on the targeted binding and internalization of the protein, GlaS, in CSC derived from triple-negative human breast cancer patients as marked by CD44 protein expression on lineage negative tumor cells." (PMID 39605477, 2024). "We treated HCC1500, CAL-51 and MDA-MB-231 with typical chemotherapies for breast cancer, 5-FU, PTX, and DOX, for 5 days and measured CSC marker expressing cells CD133+/CD44+ by flow cytometry and also by measuring total cell survival upon these chemotherapy reagent treatments." (PMID 38678032, 2024). "Nevertheless CSC-related chemo-radio-resistance in breast cancer has been further investigated, the existence of an intrinsic increase in CD-44 expression due to RT has not been already quantified." (PMID 38172135, 2024). "Furthermore, CD44+CD24− CSCs have been found to be a diverse population compared to LCs, and the two subsets co-exist together within breast cancer." (PMID 39408880, 2024). "Additionally, in the breast cancer cell line MDA‐MB‐231, ivermectin was shown to preferentially inhibit the CD44+/CD24− CSCs subpopulation." (PMID 38783892, 2024). "Currently, BCSCs are usually identified by expression of specific phenotypes; CD44+/CD24−/low and/or CD133+ are most frequently used, and it is identified as a small subpopulation of heterogeneous breast cancer cells with strong self-renewal and proliferation properties." (PMID 39469631, 2024). "CD44 and CD63 were stained in samples from 101 breast cancer cases from Peruvian women." (PMID 39430073, 2024). "An absence of CD44 can lead to a decrease of invasion and adhesion of breast cancer cells to ECs in vitro, while having no impact on cell proliferation." (PMID 38791985, 2024). "The heightened expression of CD-44 in cancer cell lines, including MCF-7, MDA-MB-468, and MDA-MB-23152, along with its strong affinity for hyaluronic acid (HA), has garnered significant attention in the context of breast cancer treatment." (PMID 38172135, 2024).
breast carcinoma (continued). "Previous work showed that the application of FSS can enrich the CSC-like subpopulation (CD44+/CD24−) in MCF-7 breast cancer cells but not in MDA-MB-231 breast cancer cells that already have a high percentage of CSC-like subpopulation." (PMID 39062471, 2024). "Also, polyphenols extracted from Artemisia annua L. showed anticancer effects by suppressing CD44 and MMP9 in radio‐resistant MDA‐MB‐231 human breast cancer cells." (PMID 38783892, 2024). "Astonishingly, Pin1 expression is elevated approximately 6-fold higher in CD24−/CD44+ breast cancer cells (CSCs) relative to non-CD24−/CD44+ breast cancer cells (non-stem cancer cells)." (PMID 38745861, 2024). "In breast cancer MCF7 cells, the TWIST is a master transcription factor that promotes the epithelial-mesenchymal transition (EMT) as well as the production of BCSC markers (CD44, ALDH1)." (PMID 39850890, 2024). "Additionally, we found elevated Cd44 expression in tumor cells derived from the aggressive 4T1 and HC11/R1-LM models of breast cancer." (PMID 36723776, 2023). "Importantly, we detected a significant reduction in CD44+ breast cancer cells in the S02 treat group, implying that USP22 pharmacological inhibition attenuates either the breast cancer stem cell self-renewal or their survival." (PMID 37398311, 2023). "In addition, Villard and collaborators showed that CD44, a CSC marker, controls the TF expression in the MDA-MB-468 breast cancer cell line, and, consequently, its procoagulant activity." (PMID 38201433, 2023). "Meanwhile, Homophilic CD44 interactions between tumor cells and subsequent CD44–PAK2 interactions mediate migration and aggregation of circulating tumor clusters in breast cancer organoids, with aggregated tumor cells promoting destructive metastasis of tumors." (PMID 37693042, 2023). "Of note and unlike CD-49f, the expression of the breast cancer stem cell marker CD44 was observed to be increased in the fraction of EpCAM-positive CTCs." (PMID 36823365, 2023). "Furthermore, two distinctive stem cell populations were identified in primary human breast cancer cells: CD44-, CD24+, ER+, TGFB-RII- or CD44+, CD24-, ER-, TGFB-RII+ with the latter only being able to undergo EMT due to TGF-β treatment." (PMID 36831452, 2023). "A study found that a cell population isolated from malignant human breast cancer-derived pleural effusions was detected with high expression of CD44 and low or no expression of CD24 (CD44+CD24−/low)." (PMID 37237509, 2023). "A second trial is underway to evaluate prognostic value of stem cell related markers (CD24, CD44, CD326 and EPCR) for predicting breast cancer recurrence in tumor stages 0-II, but it was withdrawn for lacking of financial support (ClinicalTrials.gov Identifier: NCT01265225)." (PMID 37919766, 2023). "Similarly, in human-derived breast cancer cells, a higher proportion of CD24-/CD44 + subpopulation indicates stronger stemness, while a lower proportion of CD24-/CD44 + subpopulation suggests weaker stemness." (PMID 38031089, 2023). "Si-RNA mediated knockdown of RBFOX2 did not alter the level of inclusion of exons v8-v10 into CD44 mRNA in both non-transformed mammary epithelial cell line NMuMG and epithelial murine breast cancer cell line PY2T under normal conditions and TGF-β-treatment." (PMID 38106992, 2023). "To further gain insight into the mechanistic basis of combination therapy in the 4T1 breast cancer model, we harvested draining lymph nodes and stained with fluorescent dye-conjugated anti-CD3, anti-CD4, anti-CD8, anti-CD44, and anti-CD62L antibodies for flow cytometry." (PMID 37190294, 2023). "Although CD44+/CD24- is considered a marker of BC stem cells, CD24 has been historically identified as a marker of cell signaling in tumors and recently has been reported as an anti-phagocytic surface protein on breast cancer cells." (PMID 37298091, 2023).
breast carcinoma (continued). "A comparative study of five patients with breast cancer and ten patients with NSCLC looked at both xCT and CD44 expression, finding a significant correlation of 18F-FSPG SUVmax at 60 min p.i. with both xCT (p = 0.68, p < 0.01) and CD44 expression (p = 0.77, p < 0.01)." (PMID 38067277, 2023). "According to published data, pre-operative treatment with oral doxycycline (200 mg per day) for two weeks led to a substantial reduction in CD44+ CSC number, ranging from 17.65% to 66.67%, in tumor samples from eight out of nine breast cancer patients (p-value < 0.005)." (PMID 37511298, 2023). "Interestingly, 4-MU has been shown to reduce HA synthesis and HAS2 and CD44 expression, but increases HYAL1 and HYAL2 in breast cancer cell lines, and to a greater extent in ER− cells." (PMID 37568628, 2023). "CXCL12 stimulates the proliferation of CD44-positive and CD24-negative breast cancer stem cells." (PMID 37496657, 2023). "CD44 alternative splicing was differentially regulated during the EMT, resulting in a switch in expression from CD44v to CD44s among human immortalized epithelial mammary cells, as well as breast cancer progression." (PMID 37835592, 2023). "Using methylation analyses in primary breast cancer specimens, Kagara and colleagues found that MSI-1 promotor methylation (which was inversely correlated with gene expression) was lowest in TNBC, similar to other stem cell markers, including CD44 and CD133." (PMID 37620963, 2023). "Moreover, individual CSCs in SCC (CD44+CD34+ITGA6+), lung cancer (ASCL1+/CGRP+ neuroendocrine cell) and breast cancer (CD44+CD24-, GSE124887) show concurrent activation of stemness genes, nuclear factors and mitochondrial components." (PMID 37463926, 2023). "Indeed, the mevalonate precursor enzyme HMGCS1 is a marker of CSC enrichment in breast cancer, whereas CD36, the receptor for the palmitic acid, is overexpressed in CD44-positive metastasis-initiating cells in oral squamous cell carcinoma." (PMID 36732018, 2023). "However, in breast cancer, the CD44+/CD24− cell population, also known as “breast CSCs,” exhibits considerably greater tumorigenic capability than the CD44+/CD24+ cell population." (PMID 38137380, 2023). "Both CD44 and HIF signals contribute cancer stemness and maintaining CSCs in breast cancer." (PMID 37064130, 2023). "In the breast cancer cell lines we studied, a negative shift in CD44 expression was observed upon long-term treatment with cytochalasin D." (PMID 37399498, 2023). "Similar results have been obtained in breast cancer (MDA-MB-231) and osteosarcoma (MG-63 and U2OS) cell lines; CD44 knockout or CD44 silencing in these cell lines (which express high CD44 levels on basal conditions) drastically reduced the migration and invasion rate compared with wild-type cells." (PMID 37511533, 2023). "Human CD44+/CD23-low breast CSCs were found to undergo apoptosis after 2-DG treatment and exhibited higher sensitivity to doxorubicin, a chemotherapy agent serving as the backbone of breast cancer therapeutics." (PMID 38067114, 2023). "We found that, when these breast cancer cell lines lost their attachment to the extracellular matrix, they accumulated a subtype of cancer stem cells (CSC) that expressed the surface markers of stem cells (e.g., CD44+CD24−)." (PMID 36979915, 2023). "During this process, breast cancer cells are switched between non-CSCs and CSCs by selective splicing of CD44 into CD44v or CD44s, and cancer cells with high levels of CD44v lose CSC stemness, while those with high levels of CD44s gain CSC stemness." (PMID 37370081, 2023). "Notably, cell surface antigens like CD44, CD24, and ESA have been effectively harnessed to isolate cancer stem cell (CSC)-like populations from breast cancer cell lines and primary tissues." (PMID 38001753, 2023). "Moreover, it has been demonstrated that hnRNPM precisely controls CD44 splice isoform switching during EMT and acts in a mesenchymal-specific manner in breast cancer cells." (PMID 38106992, 2023).
breast carcinoma (continued). "Our results showed that knockout of NONO in breast cancer cells significantly reduced the number of CD24−/CD44+ expressing cells." (PMID 37370134, 2023). "Clinically, histological analyses also revealed that breast cancer tissues from TNBC patients exhibited enriched CD44+/CD24− and ALDH1+ expression levels compared to non-TNBC tissues." (PMID 36230821, 2022). "Indeed, the HA receptor, CD44, has been detected in U-2OS/DX580 and K7M2 cells, and is also expressed in breast cancer as MDA-MB-231 cells." (PMID 36232858, 2022). "snoRNA chips (Oebiotech, Shanghai, China) included 248 snoRNAs that were employed to investigate the differential snoRNAs expression between BCCs (breast cancer cells) and BCSCs, which revealed that SNORA38 was significantly overexpressed in CD44+CD24− subgroup." (PMID 36158687, 2022). "Studies have demonstrated that SPP1 could interact with CD44 in prostate cancer, GBM, and breast cancer." (PMID 35067176, 2022). "Interestingly, Hyaluronic acid has a strong affinity for the CD44 and hyaluronan-mediated motility (RHAMM) receptors, which are overexpressed by breast cancer cells, resulting in a strong targeted capacity for tumor cells." (PMID 35875198, 2022). "A switch from CD44v to CD44s is required for EMT in breast cancer cell line models although the functional significance of CD44 in maintaining EMT was not established." (PMID 35931675, 2022). "CD44 and HMGA1 are well-known markers of CSCs in breast cancer." (PMID 35611554, 2022). "Additionally, a decrease in the BCSCs’ CD44+CD24− and ALDH1+ populations was observed, with minimal adverse reactions registered in breast cancer patients." (PMID 35326385, 2022). "Moreover, miR-203 and miR-150 can regulate the expression of DNMT3A and DNMT3B in breast cancer cells, resulting in regulation of CD44, ALDH1A3, OCT3/4, SOX2 expression, which are critical for breast cancer stem cell development." (PMID 35620052, 2022). "Moreover, by binding to its receptors CD44 and RHAMM, hyaluronan activates signaling through ERK1/2 MAP-kinase, AKT and other pathways enhancing breast cancer cell survival and proliferation." (PMID 36497283, 2022). "A subpopulation of breast cancer CSCs showed both EMT and CSC markers CD44, ABCG2, and ALDH1A1/3, which might serve as identification markers for metastasis‐initiating cells." (PMID 36226253, 2022). "Similar to our previous study on breast cancers, a subset of a few CD44+/CD45− tumor cells detached from their nests and accumulated near the capillaries or around the α-SMA+ arterioles, along with the presence of more CD44+/CD45+ lymphatic cells." (PMID 36497140, 2022). "In the poorly immunogenic 4T1 breast cancer model, nsPEFs were shown to induce immune memory response by increasing CD4+ effector memory (CD44+CD62L−) and CD8+ central memory (CD44+CD62L+) T lymphocytes that were shown to be highly cytotoxic because of produced IFNγ." (PMID 36551739, 2022). "In general, CD44 is regarded as a non-negligible marker to identify CSCs in several cancer types, such as breast cancer and colorectal cancer." (PMID 36451812, 2022). "Consistently, breast cancer tissues that were CD44+CD24− had higher levels of HIF-2α (not HIF-1α), suggesting that patients with higher level of HIF-2α are likely to have a higher percentage of stem-like cells in their cancer tissues." (PMID 35301432, 2022). "These surface markers that characterise CSCs depend largely on the type of cancer, and the best known are CD44+CD24− and ALDH in breast cancer, CD44+ and CD133+ in colon and gastric cancer, CD34+CD38− in leukaemia, CD133+ in glioblastoma and sarcoma and CD13/CD45/CD90 in liver cancer." (PMID 36078035, 2022). "More recently, we have studied the expression of five different BCSC markers (CD44, integrin subunit α6, cadherin-3, EpCAM, and ALDH1) and found significant enrichment for each biomarker in human breast cancer brain metastasis when compared with unmatched primary tumours." (PMID 35326385, 2022).